AR (androgen receptor)
Diseases named in the same sentence as AR in open-access papers (continued):
Sharing a sentence is not in itself a finding about the gene and the disease.
breast tumors (continued). "Previous studies detected MB positivity in ~40% of primary breast tumors, mainly in a mosaic-like pattern in luminal-type, estrogen receptor (ER)-positive cases, and in ~53% of prostate cancer tumors, mostly in androgen-receptor positive and poorly differentiated entities." (PMID 36223378, 2022). "In vitro studies have demonstrated that AR might decrease ER transcriptional activity probably by competing to the same binding sites as ER in breast tumors." (PMID 34234742, 2021). "A majority (~70%) of breast tumors are estrogen receptor positive, and a significant portion (~90%) of ER-positive (ER+) breast tumors are also androgen receptor-positive (AR+) which is found to be predominantly expressed in in-situ, invasive, and metastatic breast cancers." (PMID 33777799, 2021). "In breast tumors, high AR expression is negatively correlated with MYC overexpression." (PMID 33062889, 2020). "Collectively, targeting both unmodified (active) and SUMO-modified (hyperactive) forms of AR could serve as a better approach for treating tamoxifen-resistant breast tumors." (PMID 32948192, 2020). "It has been demonstrated that AR has the ability to regulate cell cycle progression of breast tumors, through activation of cell signal transduction pathways (e.g., PI3K/mTOR and MAPK) or even, by direct binding of AR to gene promoters involved in cell proliferation." (PMID 32344660, 2020). "Androgen receptor (AR) is expressed in approximately 70% of breast tumors." (PMID 31126320, 2019). "The most of breast tumors are estrogen-dependent and are characterized by a high expression of ER that could interfere with the activity of AR and vice versa." (PMID 30941159, 2019). "Here we report the characterization of human breast tumors of both genders for cistromic make-up of hormonal regulation in human tumors, revealing genome-wide chromatin binding landscapes of ERα, AR, PR, GR, FOXA1, and GATA3 and enhancer-enriched histone mark H3K4me1." (PMID 29396493, 2018). "Bicalutamide is effective in androgen receptor (AR)-positive breast tumors." (PMID 29642934, 2018). "In addition, we present the first set of DNA binding data in breast tumor specimens for other members of the steroid hormone receptor family: AR, GR, and PR." (PMID 29396493, 2018). "Although AR levels have been linked to outcomes in women who already have breast tumors, the study authors found no such association between AR expression and disease risk while women were still cancer-free." (PMID 30276234, 2018). "Various reports have suggested that breast tumors lacking AR expression are associated with a shorter disease-free interval and worse OS than those with AR-positive tumors." (PMID 29912871, 2018). "Since a majority (~70%) of breast tumors found to express ER and a significant portion (~90%) of ERα+ breast tumors are AR+, but it's still unknown whether AR plays any role in this process." (PMID 29254284, 2017). "AR expression is lower in ERα- breast tumors and higher in ERα+ breast tumors." (PMID 29254284, 2017). "In addition, C1orf64 closely correlated with AR expression in primary and metastatic breast tumors and C1orf64 expression was relatively higher in breast tumors with a lower grade and lobular histology." (PMID 28915724, 2017). "Additionally, AR expression has been identified in 70%–90% of breast tumors, similar to the frequency of ER expression in breast tumors." (PMID 28067809, 2017). "AR is highly expressed in both primary (~80%) and metastatic (~60%) breast tumors." (PMID 28134791, 2017). "Results in the current study showed that pre-/perimenopausal patients were at increased risk of developing breast tumors not only negative for ER and PR, but also positive for AR." (PMID 27340922, 2016).
breast tumors (continued). "The results indicated that higher expression of Lin28A may enhances expression of AR and promotes tumor growth of ER-/Her2+ breast tumor cells via regulation of c-myc in vivo." (PMID 27494865, 2016). "Importantly, we provide ex vivo evidence that AR-V7 is upregulated by the AR antagonist enzalutamide in primary breast tumors." (PMID 26554309, 2015). "AR is known to be expressed in many breast tumors and is seen as a potential drug target." (PMID 26043920, 2015). "AR is expressed in normal breast cells, and up to 85% of breast tumors are AR positive." (PMID 26456774, 2015). "The association of these two neoplasms has not been reported until now and we will speculate on the proliferative role of severe hyperandrogenism on clusters of AR positive (AR+ve) breast tumour cells." (PMID 23816265, 2013). "Interestingly, expression of the androgen receptor (AR) in primary breast tumors and metastatic lesions predated the discovery of ERβ." (PMID 24324894, 2013). "Although largely co-expressed with ER, AR can also be overexpressed in ER(-) breast tumors." (PMID 23663520, 2013). "In that context, it is worth mentioning that 70% to 90% of primary breast tumors express the AR." (PMID 18275596, 2008). "AR inhibition may be an effective strategy for growth inhibition of AR+, ER+ breast tumors." (PMID 33062889, 2020). "The answer to this puzzling expression pattern may be in androgen receptor (AR), another steroid hormone receptor that is highly expressed in some breast tumors, has overlapping target genes with ER, and is on average eight times more highly expressed in HER2E compared to non-HER2E tumors." (PMID 29382369, 2018). "However, the positive or negative effects depend on the type of androgen used, e.g., aromatizable testosterone (T) or non-aromatizable dihydrotestosterone (DHT), but also on the ERα and AR status of the breast tumor cell and aromatase activity in the surrounding breast fibroblasts." (PMID 29083379, 2016). "Indeed, we recently analyzed intra-tissue genetic heterogeneity in the AR gene in both cancer and non-cancer tissues taken from breast tumors and quantified AR variants in individual tissue samples using a new NGS technique." (PMID 24885908, 2014). "Finally, our study demonstrates that we could accurately identify MA breast tumors by AR pathway analysis by qRT-PCR, in addition to HER2 or GCDFP15 protein overexpression by IHC." (PMID 23663520, 2013). "Interestingly, we observed a significant enrichment of the drug-modulated direct AR-activation targets among genes with higher expression in ER- breast tumors, while conversely, the direct AR-repression targets were significantly enriched among genes with higher expression in ER + breast tumors." (PMID 22849360, 2012). "However, recent molecular classifications have identified subsets of breast tumors withhigh androgen receptor expression, including "luminal androgen receptor (LAR) tumors" and "molecular apocrine tumors" (MATs), which mayhave implications for targeted therapies." (PMID 40230896, 2024). "AR expression was consistent with an immune-deserted environment based on our findings and previous studies on HER2+ metastatic breast tumors and TNBCs." (PMID 37085500, 2023). "The top eight genes that negatively correlated to POLR3G expression (MLPH, FOXA1, SPDEF, AR, SIDT1, AGRP2, XBP1, GATA3) are typically overexpressed in ER+ breast tumors as compared to ER- breast tumors." (PMID 36497214, 2022). "The AR and ESR1 transcript levels were evaluated by real time PCR on all the 275 breast tumor samples." (PMID 34234742, 2021). "In ER-/HER2 + breast tumors, WNT7B was shown to be a direct transcriptional target of the androgen receptor (AR) and predicted to be regulated by Nuclear respiratory factor 1 (NRF1)." (PMID 33625717, 2020).
breast tumors (continued). "In particular, we examined promoter methylation status of genes involved in signal transduction and hormone signalling, including AR, ESR1, hTERT, MYC, RASSF1 and WNT in male breast tumors, paired blood samples and normal tissues." (PMID 29731982, 2018). "Using candidate-gene approach, we examined the promoter methylation level of AR, ESR1, hTERT, MYC, RASSF1 and WNT1 in 69 male breast tumors and corresponding blood samples, 7 normal breast tissues and 8 normal lymph node samples." (PMID 29731982, 2018). "Consistently with this model, AR and FOXA1 mRNA expression positively correlated with percentage of ER and PgR expressing cells in our cohort of breast tumours, but only FOXA1 mRNA expression negatively correlated with miR-9-5p expression." (PMID 28345661, 2017). "Breast tumors with FOXA1 overexpression have been reported to have a good prognosis, and we expect that the expression of FOXA1 will be tested in AR-positive TNBCs in the future." (PMID 28067809, 2017). "Our findings suggest that PIP is overexpressed in ER-/AR+ breast tumors and PIP expression is highly regulated by AR-ERK signaling in both in vitro and in vivo molecular apocrine models." (PMID 22817771, 2012). "AR-positive cells were present in 85% (61/72) of breast tumours, and 98% (43/44) of PSA-positive and 92% (44/48) of GCDFP-15-positive tumours were also positive for AR." (PMID 9703283, 1998). "Carcinoma with apocrine differentiation is characterized in the fifth edition of the WHO Classification of Breast Tumors by apocrine morphology in greater than 90% of tumor cells combined with an ER negative, PR negative, AR positive immunophenotype." (PMID 37306115, 2024). "Among these genes, AR has been found to stimulate breast tumor growth in the absence of the estrogen receptor, making it a promising molecular target in the treatment of TNBC." (PMID 37996875, 2023). "AR stimulates breast tumor growth in the absence of estrogen receptor (ER), and it has become an emerging molecular target in TNBC treatment." (PMID 35768871, 2022). "BT474 cells express both ER and AR, whereas LNCaP cells do not express ER, and higher androgen receptor expression was detected in ER+ breast tumors." (PMID 36438817, 2022). "AR prevalence is higher in ERα-positive early breast tumors than ERα-negative ones (74.8% vs. 31.8% of cases respectively)." (PMID 31952272, 2020). "Breast tumors that are ER+ are more likely to be AR+ compared to tumors that are ER−67, and AR status is related to ER and PR status but independent of the status of HER268." (PMID 33062889, 2020). "Since majority of the African American breast tumors where AR negative, we further observed that African American patients showed very early death (1400 days) as compared to their white counterparts (3000 days)." (PMID 29912871, 2018). "TN tumors with a luminal AR-driven (LAR) profile, defined as expressing AR and downstream AR targets and co-activators, have been shown to benefit less from standard neoadjuvant chemotherapy compared to other TN breast tumors." (PMID 29382369, 2018). "AA breast tumors express AR at lower rates compared to Whites, independent of ER and PR expression (p<0.0001)." (PMID 29912871, 2018). "Importantly, by targeting the AR pathway using bicalutamide, the growth of DHT-stimulated ER−/HER2+ breast tumor cells in vivo was inhibited." (PMID 28134791, 2017). "A molecular subtype of BCa referred to as the molecular apocrine subtype, which included those non-basal-like ER− breast tumors that were also AR+, was defined based on microarray expression profiling." (PMID 28134791, 2017). "91% of the breast tumors with positive expression of ER, PR, or HER2 also expressed the AR." (PMID 29083379, 2016).
breast tumors (continued). "Interestingly, this study also demonstrated that breast tumors with the highest expression of VDR, ER, and Androgen Receptor (AR) had the best prognosis." (PMID 24982636, 2014). "Loss of AR expression is associated with early onset, high nuclear grade and negative ER, PR and HER2 expression status in breast tumours." (PMID 22471922, 2012). "In conclusion, PSA and GCDFP-15 immunoreactivity was dependent on the presence of AR, but not ER or PR in primary breast tumours." (PMID 9703283, 1998). "To investigate further the androgen-responsiveness of human breast tumours, we examined the immunohistochemical expression of the AR and two androgen-regulated proteins, prostate-specific antigen (PSA) and gross cystic disease fluid protein-15 (GCDFP-15), in 72 primary breast tumours." (PMID 9703283, 1998). "Focal positivity of apo-D staining, which did not always co-localise with AR-positive cells, was observed within breast tumours." (PMID 8883401, 1996). "Similarly, 57 and 64% of human breast tumor tissues expressed ACK1 and AR, respectively." (PMID 35768871, 2022). "Further, our data indicate that anti-androgen or anti-estrogen therapies may be effective radiosensitisation strategies in some, but not all AR+/ER+ breast tumours, suggesting a need for additional biomarkers of response for AR and/or ER antagonists." (PMID 35618789, 2022). "The same study showed that the administration of antiandrogen enzalutamide decreased both ERα-positive and ERα-negative/AR-positive breast tumor growth, suggesting antiandrogen therapy as a novel effective treatment for patients with de novo resistance to hormone therapies." (PMID 31952272, 2020). "Daemen and Manning explored HER2 amplification in 3155 breast tumors and found that the HER2–enriched (HER2E) subtype had a distinct transcriptional landscape independent of HER2-amplificated (HER2A) that reflected and confirmed how AR signaling can replace ER-driven tumorigenesis." (PMID 30941159, 2019). "Molecular apocrine tumors were known to express AR but not ER, however studies showed that these tumors have an expression profile like that of ER+ luminal breast tumors, and the likely mechanism could be through the AR signaling pathway." (PMID 29254284, 2017). "Androgen receptor (AR) is expressed in 60-70% of breast tumors, independent of ER status." (PMID 27494865, 2016). "On the contrary, most ER+ve breast neoplasms are negative for AR." (PMID 23816265, 2013). "Presence of the early 5′ breakpoints in MCF-7 genes suggest that recurrent double-stranded breaks may occur in breast tumors at the gene promoter and early splicing sites due to factors not mediated by the androgen receptor." (PMID 22496636, 2012). "Moreover, AR positive breast tumors have been shown to be smaller, more often node negative, lower in histological grade and clinical stage than their AR negative counterparts." (PMID 23148692, 2012). "Additionally, overexpression of AR in the GCs of PCOS follicles may have a direct effect on ERs signaling, as reported in a study on breast tumor development showing that the overexpression of ligand-activated AR reduced ERα transactivity by sequestering coactivators like SRC-3/AIB1." (PMID 38069013, 2023). "However, in vitro evidence partly supported clinical studies and AR showed antiproliferative activity in only ER-positive breast cancers but rather AR signaling promoted tumor growth in ER-negative and human epidermal growth factor receptor 2 (HER2)-positive breast tumors." (PMID 29137314, 2017).
breast tumors (continued). "In addition, 91% of the Thai breast tumors that were positive for any of the following receptors, estrogen receptor (ER), progesterone receptor (PR), and human epidermal growth factor receptor 2 (HER2) also expressed the AR protein, while in triple negative breast tumors only 33% were AR positive." (PMID 29083379, 2016). "The finding that the breast tumour did not express ER or HER2 suggests that cell proliferation can be stimulated by androgen excess, independently by circulating estrogens concentration if AR are expressed, and is in keeping with the androgen-excess theory recently proposed by Secreto and Zumoff." (PMID 23816265, 2013).